GPX3 (glutathione peroxidase 3)
Diseases named in the same sentence as GPX3 in open-access papers (continued):
Sharing a sentence is not in itself a finding about the gene and the disease.
cancer (continued). "One antioxidant enzyme whose expression in serum/plasma has been correlated with various cancers is glutathione peroxidase 3 (GPX3)." (PMID 22017790, 2011). "Women with late stage disease (median, 18.5 ng/ml; p = 9 × 10-4) and recurrence of their cancer (median, 14.7 ng/ml; p = 1 × 10-2) had significantly lower levels of GPX3 than controls." (PMID 22017790, 2011). "On a genetic level, downregulation of GPX3 via hypermethylation of its promoter has been described in human esophageal squamous cell carcinoma tissue and primary prostrate cancer samples and cell lines." (PMID 22017790, 2011). "For instance, hypermethylation of the GPX3 promoter is a common occurrence in human cancers." (PMID 40092686, 2025). "GPX3 functions as an antioxidant enzyme in inflammatory diseases and cancers." (PMID 39562369, 2025). "Also, an increase in reactive oxygen species (ROS) can damage DNA and lead to cancer, so GPX3 is needed to counteract ROS." (PMID 41031088, 2025). "In the other direction, GPX3, identified as a stage-I salient gene here, was detected as differentially methylated in stage-2, suggesting the interpretation that change in its expression is necessary for cancer metastasis and mesenchymal transition." (PMID 39484215, 2024). "Several studies have shown reduced serum GPx3 activity in cancer patients." (PMID 38732573, 2024). "GPx3 has dual roles in cancer, either as a tumor suppressor or tumor prosurvival protein." (PMID 38483584, 2024). "Modifications in Gpx3 play a role in the regulation of various signaling pathways in cancer." (PMID 39125992, 2024). "Cancer development may be linked to alterations in GPX2 and GPX3 activities, which were associated with glutathione (C00051), oxidized glutathione (C00127), and hydrogen peroxide (C00027)." (PMID 37955007, 2023). "Previous studies have suggested that GPX3 may be involved in cancer metastasis and chemotherapy resistance." (PMID 36845676, 2023). "This suggested that acute GPX3 knockdown is indeed detrimental to established cancer growth." (PMID 36845676, 2023). "GPX3 is an effective inhibitor of cancer development and progression." (PMID 36845676, 2023). "However, in advanced cancer, the up-regulation of GPX3 in cancer cells plays a role in eliminating excessive ROS production and protecting cells from anoikis." (PMID 36845676, 2023). "We compared the expression of GPX3 in human cancers and normal tissues in several public databases." (PMID 36845676, 2023). "Notably, macrophages, especially M2 macrophages, had a consistently positive correlation with GPX3 in various cancers." (PMID 36845676, 2023). "Downregulation of GPX3 expression impairs the antioxidant capacity of cancer cells." (PMID 36845676, 2023). "Relation of GPX3 expression and the clinical characteristic of patients with cancers." (PMID 36845676, 2023). "We further investigated the potential genetic and epigenetic regulation of GPX3 in cancer." (PMID 36845676, 2023). "We investigated the function of GPX3 in the prognosis of cancers." (PMID 36845676, 2023). "Genetic changes may impact the function of GPX3 and further induce malignant transformation and affect the clinical prognosis of cancer patients." (PMID 36845676, 2023). "GPX3 plays a role in cancer occurrence, progression, and treatment." (PMID 36845676, 2023). "Knockdown GPX3 significantly decreased the ability of cancer cells to clear ROS." (PMID 36845676, 2023). "As such, numerous studies have focused on the role of GPX3 in cancers." (PMID 36358931, 2022). "In addition to detoxification, GPX3 has a significant role in cellular defense mechanisms, such as inflammation and cancer progression inhibition." (PMID 36552219, 2022). "Likewise, extracellular glutathione peroxidase (GPX3) also plays a dichotomous role in different types of cancer." (PMID 36389725, 2022). "Additionally, GPX3 over-expression similarly suppressed the proliferation and metastasis of cancer cells." (PMID 35978348, 2022).
cancer (continued). "GPx3 is considered a tumor suppressor, GPx2 seems to act at the very early stages of cancer, while selenoprotein H is a key regulator for the cell cycle, indicating the role of selenoproteins in cancer could be both preventive and therapeutic." (PMID 35682497, 2022). "This role might account for several studies showing altered levels of GPx-3 expression and/or serum activity in cancer and CVD." (PMID 33505588, 2021). "Furthermore, in addition to GPX3 other genes were highly expression in GC tissue compared with normal gastric mucosal tissue with the cancer genome atlas (TCGA) database as the validation dataset." (PMID 33976737, 2021). "Many studies have shown that methylation-mediated GPX3 inhibition may have important implications for the pathogenesis of cancer." (PMID 34926458, 2021). "Studies related to the role of GPx3 in cancer can be grouped into two categories." (PMID 32781581, 2020). "This review focuses on GPx3, which has received relatively little attention in the cancer field." (PMID 32781581, 2020). "Although oxidative stress from lipid peroxidation has been associated with increased risk of breast and esophageal cancer, changes in Se concentrations and GPx3 activity have not been linked to these cancers." (PMID 32781581, 2020). "Moreover, GPX3 reduced expression and patients' clinical data of hormonal usage, cancer family history, alcohol consumption, and smoking status were analyzed." (PMID 33392611, 2020). "From this study and others, GPX3 expression could be up-regulated after 5-aza-dC treatment in different cancer cell lines." (PMID 33369453, 2020). "Interestingly, we observed that LIUS treatment in cancer cells induced the expression of genes that regulate ROS generation while downregulating the expression of GPX3 that has the potential to exert antioxidant effects." (PMID 31355136, 2019). "In addition, many studies demonstrate that reduced ROS levels are mediated by overexpression of GPx3 in many types of cancer cell." (PMID 30260967, 2018). "In addition, GPx3 expression led to a significant reduction in ROS production by cancer cells and induced G2/M phase arrest." (PMID 30260967, 2018). "Clinical significance of GPX3 hypermethylation has been demonstrated in a number of human cancers." (PMID 27891827, 2017). "Taken together, these may probably be due to GPX3 playing different roles in initial development of cancer, and GPX3 expressed heterogeneously among different cells types like in CD34+ cells and mesenchymal stem cells." (PMID 27891827, 2017). "Our results showed that GPx3 was already significantly down-regulated in such “pre-cancer” tissues." (PMID 25333265, 2014). "Promoter hypermethylation mechanism which is a “frequent event in human cancers” may result in GPX3 gene silencing and inhibition of GPX3 expression." (PMID 24790704, 2014). "In addition, studies showed that expression and activity of GPX3 contribute to prevention of cancer initiation." (PMID 24790704, 2014). "Exploration of functional role of GPx3 in HCC could provide new evidences to apply anti-oxidant agents for cancer therapy." (PMID 25333265, 2014). "Level of expression of GPX3 protein was assessed in normal and carcinoma breast tissues using IHC." (PMID 24790704, 2014). "Thus important future studies will be validating these results and in exploring the role of GPX3 in cancer initiation, progression and outcome." (PMID 22017790, 2011). "In addition women with late stage disease (p = 5 × 10-4) and recurrence of their cancer (p = 1 × 10-2) had significantly lower levels of GPX3 than women with early stage disease." (PMID 22017790, 2011). "In addition, specific downregulation of GPX3 was found in many types of cancer." (PMID 36845676, 2023). "In addition, we preliminarily found that GPX3 expression in cancer may be epigenetically regulated, which also needs further verification." (PMID 36845676, 2023). "We speculated that GPX3 played a role in chemotherapy drug resistance in cancers." (PMID 36845676, 2023).
cancer (continued). "GPX3 may be involved in cancer processes by regulating ROS levels." (PMID 36845676, 2023). "The seemingly contradictory results of GPX3 in cancer may be closely related to ROS." (PMID 36845676, 2023). "In addition, we found that CALB2 and GPX3 could also be considered as prognostic biomarkers in pan-cancer." (PMID 37664836, 2023). "In addition, we simply predicted the regulatory mechanism of GPX3 in cancers." (PMID 36845676, 2023). "ROS buildup in tissue cells due to GPX3 inactivation may contribute to cancer growth." (PMID 35069731, 2022). "The markers GPX3, PDGFRL, RGS2, and SERPINE1 were found to be significantly increased in the high-risk group, suggesting that all of these markers may be implicated in the malignancy processes for STAD patients and may be cancer-promoting factors." (PMID 36199800, 2022). "However, GPX3 has been involved in cancer as it could suppress tumor progression in cancer cells exposed to oxidative stress." (PMID 35453573, 2022). "In addition, for the four types of cancer, only one of GPX3 or DIO1 showed prognostic value." (PMID 32316597, 2020). "In addition, we found that GPX3 expression was reduced in 21 types of cancers." (PMID 32316597, 2020). "Given that proliferative behavior is fundamental to the progression of malignant tumors, we used MTT and colony formation assays to demonstrate that upregulation of GPX3 and JUN significantly inhibits the proliferation of TC cells." (PMID 40092686, 2025). "We conducted ectopic overexpression experiments to elevate the levels of GPX3 and JUN in cancer cells." (PMID 40092686, 2025). "Overall, these results suggested that GPX3 can serve as an independent biological prognostic marker for STAD, where it appears to influence the proliferation and invasion of these cancer cells." (PMID 38322113, 2024). "Thus, targeting GPx3 may be a promising strategy in cancer treatment (see also below)." (PMID 38483584, 2024). "Se nanoparticles also decreased cancer cell viability and proliferation while increasing the mRNA expression of TXN, GPX1, GPX2, GPX3, and GPX4 in many of the cancer cell lines." (PMID 39408290, 2024). "The degree of staining for GPX3 and PPP1R26 was stronger in normal tissues than in cancer tissues; on the other hand, ZFYVE27 showed the opposite trend." (PMID 36717783, 2023). "There were widespread amplifications and deletions of five genes (GPX3, RGS2, MATN3, SLC7A2, and SNCG) across pan-cancer." (PMID 35721114, 2022). "Our qRT-PCR results confirmed that GPX3 and RGS2 were significantly downregulated in GC than in para-carcinoma tissues." (PMID 35721114, 2022). "Finally, by testing the relationship between the expression levels of these two families of selenoprotein genes in NCI-60 cell lines and drug sensitivity, we found that the TXNRD1, GPX1, GPX2, and GPX3 genes may play a role in the drug sensitivity or drug resistance of cancer cells." (PMID 33706760, 2021). "Glutathione peroxidase 3 (GPX3) is an important antioxidant enzyme that protects cells against Reactive Oxygen Species (ROS), downregulated in many cancers." (PMID 34249670, 2021). "According to the results, MGST1, GPX3, SP1, TXNRD1, MAPK14, and SOD1 presented with CNV gains among various types of cancers." (PMID 34721758, 2021). "Survival maps, i.e. heat maps of hazard ratio (HR), showed the prognostic value of GPX3 and DIO1 in pan-cancer." (PMID 32316597, 2020). "Dot plots described the differential gene expression levels with respect to GPX3 and DIO1 among the 33 TCGA cancer types." (PMID 32316597, 2020). "Based on TCGA BLCA dataset, we found that CRYAB (AUC = 0.9326, P < 0.001), ECM1 (AUC = 0.6782, P = 0.009), CGNL1 (AUC = 0.9314, P < 0.001), and GPX3 (AUC = 0.8480, P < 0.001) are effective in distinguishing HGBC tissues and normal para-carcinoma tissues." (PMID 32292720, 2020).
cancer (continued). "Further, we observed that LIUS has the tendency to induce antioxidant effects in non-cancer cells by attenuating the gene expression of NOS2 and NOS3, which promote ROS generation, while promoting the expression of antioxidant genes GPX3 and GPX7." (PMID 31355136, 2019). "Additional genes in this study, showing changes in gene expression for both the Irish and the Czech cancers were GPX2, GPX3, SELENOK, SEPHS2, SELENBP1, and SOD2." (PMID 30469315, 2018). "The methylation frequency of EPB41L3, GPX3, and COL14A1 were 31.0%, 40.5% and 31.0% in cancer patients' plasma, respectively." (PMID 25050929, 2014). "Consistent with a role for NFE2L2 in vitamin D-mediated cancer prevention, a number of NFE2L2 target genes were increased in RWPE1 cells after 1,25(OH)2D treatment, e.g. GPX3, HMOX1, AKR1C2, and TXNRD1." (PMID 20070897, 2010). "This suggests that GPX3 and JUN may exert their anti-cancer effects in TC by regulating amino acid metabolism and influencing intracellular redox balance." (PMID 40092686, 2025). "In agreement with the findings that upregulated proteins in cancer are known to transport GSH, it has been proposed that GSH may play a role in the regulation of GPx3 activity." (PMID 38483584, 2024). "In STAD patients, the genes GPX3, PDGFRL, RGS2, and SERPINE1 may be connected to the cancer process." (PMID 36199800, 2022). "The GPX3 gene tended to be down-regulated in all types of cancers except for GBM, while the other six genes were up-regulated or down-regulated in the different types of cancer." (PMID 33706760, 2021). "The expression levels of the GPX1 and GPX3 genes were positively correlated with the stromal- and immune-cell scores, and the TXNRD2 gene was negatively correlated with the stromal-cell score for all but a few cancers." (PMID 33706760, 2021). "Previous studies have suggested that high GPX2 gene expression is associated with a poor cancer prognosis, which appears to be supported by the present finding of a significant negative correlation between the GPX2 and GPX3 genes." (PMID 33706760, 2021). "ONCOMINE database was used to perform pan-cancer analysis on GPC3, GPX3 and PRICKLE1 expression." (PMID 34926458, 2021). "Consistently, the GPx3 levels were reported to be down-regulated in aggressive inflammatory breast cancer (IBC) carcinoma tissues compared to non-IBC tissues, and this down-regulation was associated with hypermethylation of the GPx3 promoter." (PMID 32571353, 2020). "Although the down-regulation of GPx3 was shown in several malignancies, the clinical significance and functional role of GPx3 in cancer development have not been well illustrated." (PMID 25333265, 2014). "We found that GPX3 mRNA and protein expression levels were downregulated in the carcinoma tissues of IBC compared to non-IBC." (PMID 24790704, 2014). "Results revealed a significant increase (P = 0.04) in the M/U ratios of GPX3-MSP products in IBC versus non-IBC carcinoma tissues." (PMID 24790704, 2014). "Furthermore, GPX3 alterations regulate several signaling pathways, including NF-κB, Wnt/β-catenin, and JNK signaling, which influence the proliferation and metastasis of cancer cells 24,29,31." (PMID 37790850, 2023). "Hence, the classification effectiveness of ten biomarkers which was assessed overall was based on GPX2 and GPX3 as factors from the enriched pathways and CAV1, ENO1, NQO1, and P4HB as factors from functional classes to determine whether a patient had cancer." (PMID 37955007, 2023). "In addition, IBC carcinoma tissues showed a significant increase in the promoter hypermethylation of GPX3 gene compared to non-IBC." (PMID 24790704, 2014). "Promoter hypermethylation of GPX3 gene was detected in carcinoma tissues not normal breast tissues." (PMID 24790704, 2014).
cancer (continued). "Notably, about 33% (15/45) of the “normal" gastric tissues adjacent to cancers without neoplastic changes also displayed downregulation (relative expression, ≤0.5) of GPX3 mRNA, as normalized to the value of the average of all normal samples." (PMID 23071548, 2012). "However, downregulation of GPX3 in IBC versus non-IBC carcinoma tissues suggests that GPX3 may play a role in IBC disease progression." (PMID 24790704, 2014). "When we compared carcinoma tissues of IBC with non-IBC samples, we detected a significant decrease in mRNA and protein expression of GPX3 in IBC tissue samples versus non-IBC tissue samples." (PMID 24790704, 2014). "We compared the level of mRNA expression of GPX3 in non-IBC and IBC, and our results revealed that mRNA expression level of GPX3 expression in non-IBC carcinoma tissues was statistically significant (P = 0.036) higher than that in IBC." (PMID 24790704, 2014).
infection (14 papers, 2011 to 2026). The state of being infected such as from the introduction of a foreign agent such as serum, vaccine, antigenic substance or organism. "In contrast to the observed drop in basement membrane associated Gpx3 during viral replication period (5–7 dpi), the levels of alveolar Gpx3 gradually increased following infection." (PMID 22355371, 2012). "First, we found that the infection efficiency of GPX3 in cells was positively correlated with MOI, which gradually increased with the increase of MOI value." (PMID 41492475, 2026). "As the main extracellular antioxidant enzyme responsible for eliminating peroxides and maintaining REDOX balance, the upregulation of GPX3 is likely to represent a host compensatory mechanism to combat infection-induced oxidative stress." (PMID 41428679, 2025). "Secondly, the biological functional validation of the proteomic data requires further investigation, such as exploring the regulatory mechanisms of key node molecules (e.g., GPX3 or ITLN1) in infection models using gene editing technologies." (PMID 41428679, 2025). "For functional annotation of KEGG pathway enrichment, in the acute infection stage, we observed significant enrichment of upregulated mRNAs (Gpx2 and Gpx3) in the glutathione metabolism pathway." (PMID 38229193, 2024). "Cap1, Gpx3 and Ybp1 are also vital for C. albicans virulence in a Galleria mellonella model of infection, and Cap1 is important for virulence in a Caenorhabditis elegans infection model in nematode hosts that have a functional NADPH oxidase." (PMID 25723552, 2015). "Specifically, both the Clara-enriched Prdx6 and the AT2-enriched Gpx3 are maintained, possibly by compensatory expression system during infection." (PMID 22355371, 2012). "Glutathione peroxidase 3 was identified in three spots, two of which changed in response to infection." (PMID 21297942, 2011). "Furthermore, plasma GPX3 is essential in mitigating reactive oxygen species damage, which can be induced by multiple stressors including physical exertion, infection, and inflammation." (PMID 40073124, 2025). "Loss of Cap1 or its regulators Gpx3 and Ybp1 attenuates virulence in some, but not all infection models." (PMID 25723552, 2015). "Therefore, it is possible that plasma Gpx3 gains access to the lungs due to increased permeability during infection." (PMID 22355371, 2012). "Thus, the reduction in AT2-secreted Gpx3 is likely masked by the influx of antioxidants in the plasma, thus providing alternative mechanism for maintaining the balance of antioxidants during infection." (PMID 22355371, 2012). "The expression of CAMK2B, GPX3, and SOD2 in the infection + NAC group was lower than that in the infection group (p < 0.05)." (PMID 38149012, 2023).